IFNGR2 (interferon gamma receptor 2)
Diseases named in the same sentence as IFNGR2 in open-access papers (continued):
Sharing a sentence is not in itself a finding about the gene and the disease.
pulmonary tuberculosis (2 papers, 2014 to 2016). A bacterial infection that affects the lungs and is caused by Mycobacterium tuberculosis. "Similarly, previous studies have reported an age-dependent association between pulmonary tuberculosis and SNPs in genes including IFNGR2, TOX and NRAMP1." (PMID 25360588, 2014). "Interferon Gamma Receptor 2 (IFNGR2) plays a role in activation of macrophages and regulation of Th1 response to intracellular pathogens, with genetic variants previously associated with atopic asthma and pulmonary tuberculosis." (PMID 27814717, 2016).
rectal cancer (2 papers, 2014 to 2017). A primary or metastatic malignant neoplasm that affects the rectum. "A previous study examined genetic variation in IFNG, IFNGR1, IFNGR2 and IRF1-9 with the risk and survival of colon and rectal cancer." (PMID 25350395, 2014). "In particular, the authors demonstrated that the IRF2 mutational status is associated with both colon and rectal cancer, whereas mutations in other genes involved in IFN signaling pathway were uniquely associated with colon (IFN-γ and IRF3) or rectal cancer (IFNGR1, IFNGR2, IRF4, IRF6, and IRF8)." (PMID 28798748, 2017).
schizophrenia (2 papers, 2020 to 2021). A major psychotic disorder characterized by abnormalities in the perception or expression of reality. "Nevertheless, recent research has reported that the Interferon Gamma Receptor 2 (IFNGR2) may act as a risk factor for the development of schizophrenia in men only." (PMID 34575706, 2021).
Sepsis (2 papers, 2022 to 2023). Sepsis is defined as life-threatening organ dysfunction caused by a dysregulated host response to infection. "Likewise, phosphorylation of STAT3 was markedly augmented at 24 h after the onset of sepsis, in combination with simultaneous induction of IFNGR2." (PMID 35832091, 2022).
Aleutian disease (1 paper, 2024). "From this, we identified several candidate genes contributing to the growth and feed efficiency (ARID1B, APPL1, TOX, and GPC5), reproduction (GRM1, RNASE10, WNT3, WNT3A, and WNT9B), pelt quality (MYO10, and LIMS1), and Aleutian disease tests (IFNGR2, APEX1, UBE3A, and STX11)." (PMID 38167844, 2024).
brainstem tumors (1 paper, 2024). "Our study characterizes the prognostic impacts of TGFB2 and IFNGR2 in brainstem tumors, which provide potential insights into the prognostic role of these molecules in pbDMG patients." (PMID 38255296, 2024).
breast carcinoma (1 paper, 2013). "Our data suggest that several pathway members, such as Stat1, Ifngr2, Tgtp1, Ifit1, Gbp1 and Gbp3, may be suitable biomarkers for residual disease in breast cancer patients treated with cytotoxic chemotherapy." (PMID 23520493, 2013).
brucellosis (1 paper, 2024). Brucellosis is a bacterial infection that spreads from animals to people via unpasteurized dairy products or by exposure to contaminated animal products or infected animals. "In brucellosis patients, the expression levels of many typical IFN‐γ/IFN‐I response genes, including IFITM3, B2M, GBP1, IRF1, IFI30, IFNGR2, and so forth, were higher than those in controls." (PMID 39135683, 2024).
cardiac hypertrophy (1 paper, 2022). "Of note, MA Rage−/− mice evidence a transcriptional drift of genes related to the regulation of cardiac cell growth and hypertrophy (Cluster 2B): some of them are positive regulators of cardiac hypertrophy, such as Edn1, while others, such as Ifngr2-Naftcs, mediate antihypertrophic effects." (PMID 36232442, 2022).
chronic granulomatous disease (1 paper, 2025). Chronic granulomatous disease (CGD) is a rare primary immunodeficiency, mainly affecting phagocytes, which is characterized by an increased susceptibility to severe and recurrent bacterial and fungal infections, along with the development of granulomas. "Among them, IL12B and LTA are already established therapeutic targets for PsO, and IFNGR2 has been developed as a therapeutic target for chronic granulomatous disease." (PMID 40564099, 2025). "Actimmune, which binds to IFNGR2, is known to alleviate severe malignant osteoporosis and chronic granulomatous disease and may potentially be repurposed for PsO." (PMID 40564099, 2025).
colitis (1 paper, 2022). Inflammation of the colon. "In a BALB/c mouse model of dextran sodium sulfate-induced colitis, IFNGR2 was significantly up-regulated." (PMID 35204186, 2022).
cutaneous squamous cell carcinoma (1 paper, 2021). "Moreover, rare multiple cutaneous squamous cell carcinoma was reported in a patient with a deficiency of IFNGR2 expression." (PMID 33916009, 2021).
diabetes (1 paper, 2018). "However, using a CD4+ T cell-mediated adoptive transfer model of autoimmune diabetes we observed that even though diabetes does not develop in Ifnγr2-deficient recipient mice, IFNγ-induced MHC class II on IECs is not important for development of insulitis or diabetes." (PMID 30555479, 2018).
gastric cancer (1 paper, 2021). A primary or metastatic malignant neoplasm involving the stomach. "An IFNGR2 polymorphism (Ex7-128 C > T) was reported to increase the risk of gastric cancer in a population-based study of Poland." (PMID 34257587, 2021). "Thus, IFNGR2 is a gene related to Th1 cell-mediated immune responses in gastric cancer." (PMID 34257587, 2021).
Giardia infections (1 paper, 2022). "Several cytokine receptors are differentially expressed during the Giardia infections, including IL11RA, IFNGR1, IFNGR2, IL10RA, and ACKR3." (PMID 35573800, 2022).
inclusion body myositis (1 paper, 2022). A slowly progressive degenerative inflammatory disorder of skeletal muscles characterized by late onset weakness of specific muscles and distinctive histopathological features. "Patients with inclusion body myositis had segmental IFNGR2 up-regulation in myofibroblast membranes, which was positively correlated with the number of adjacent CD8+ T cells." (PMID 35204186, 2022).
measles (1 paper, 2020). A highly contagious viral infection caused by the measles virus. "Paradoxically, there was also a report showing no adverse sequelae in humans with genetic defects in both the IFNAR1 and IFNGR2 genes after attenuated measles vaccination." (PMID 32300346, 2020).
Multiple Organ Failure (1 paper, 2021). A progressive condition usually characterized by combined failure of several organs such as the lungs, liver, kidney, along with some clotting mechanisms, usually postinjury or postoperative. "Multiple organ failure observed in the patient presented could be related to the triple gene dose of four interferon receptors (IFNAR1, IFNAR2, IFNGR2, and IL10RB) located at 21q22.11." (PMID 34760326, 2021).
myocardial infarction (1 paper, 2021). Gross necrosis of the myocardium, as a result of interruption of the blood supply to the area, as in coronary thrombosis. "Interferon-gamma receptor 2 (IFNGR2), the parent gene of circRNA_0002113, was reported to be involved in the progress of myocardial infarction." (PMID 35127703, 2021).
nasopharyngeal carcinoma (1 paper, 2025). A carcinoma arising from the nasopharyngeal epithelium. "The expression levels of PD-L1 and interferon gamma receptor 2 (IFNGR2) are increased in nasopharyngeal carcinoma (NPC)." (PMID 40710359, 2025).
osteoarthritis (1 paper, 2020). A noninflammatory degenerative joint disease occurring chiefly in older persons, characterized by degeneration of the articular cartilage, hypertrophy of bone at the margins and changes in the synovial membrane. "Interestingly, by mining a published microarray database (GSE57218), we found that IFN-related genes (STAT1, IFNGR2, NCAM1, MID1) were highly elevated in the cartilage tissues of osteoarthritis patients." (PMID 32202492, 2020).
parasitic infections (1 paper, 2015). "As a consequence of defective negative regulation, mice harboring DCs devoid of IFNγR2 exhibited unrestrained IFNγ responses and suffered exacerbated immune-mediated pathology during parasitic infections." (PMID 25658840, 2015).
preeclampsia (1 paper, 2015). Preeclampsia is a hypertensive disorder of pregnancy that is characterized by new-onset hypertension with proteinuria presenting after 20 weeks of gestation, and depending on mild or severe forms may initially present with severe headache, visual disturbances, and hyperreflexia. "The amount of insulin resistance genes (IFNGR2 and NFX1) may correlate with the preeclampsia syndrome, which is regarded as a key feature of preeclampsia genesis." (PMID 26089598, 2015).
renal carcinoma (1 paper, 2023). A carcinoma arising from the epithelium of the renal parenchyma or the renal pelvis. "IFNGR2 codes for the IFN-γ receptor, which has been found to mediate a non-immunogenic tumor phenotype associated with checkpoint inhibitor resistance in renal carcinoma." (PMID 36936916, 2023).
tumor (45 papers, 2009 to 2025). "It is also worth noting that although PAK1 and IFNGR2 satisfy the conditions of HR > 1 and p < 0.05, they are upregulated genes and cannot be considered as tumor risk factors." (PMID 37107646, 2023). "However, reintroducing IFNγR2 in two tumor models restored progressive tumor growth indicating that the lack of IFN-γ signaling was the causative factor resulting in spontaneous tumor control." (PMID 32001684, 2020). "LGG patients expressing high levels of TGFB2 and IFNGR2 are over-represented in IDH wild-type tumor samples, suggesting that TGFB2 and IFNGR2 mRNA can be therapeutically targeted in these high-risk patients." (PMID 38539537, 2024). "We selected three genes known to modulate tumor immunogenicity (IFNGR2, STAT1 and MYC) for which 2 sgRNA pools were produced." (PMID 39497819, 2024). "These present studies detail the interaction between TGFB2 and IFNGR2 in the tumor microenvironment, resulting in a prognostic impact on OS outcomes in pbDMG patients." (PMID 38255296, 2024). "Consistent with previous reports, we found enrichment of sgRNA targeting genes associated with both IFN-gamma signalling (Jak1, Jak2, Ifngr2) and TNF signalling (Tnfrsf1a, Fadd) in tumour cells resistant to CAR-T cell killing." (PMID 39261596, 2024). "After the GSEA pathway enrichment analysis, the IL2-STAT5 pathway was enriched by the higher expression of RUNX1 and IFNGR2, which were involved in cell proliferation, migration, invasion, and tumor immunity." (PMID 36321611, 2023). "At 7 and 14 days after mesenteric tumor inoculation, IFNGR2 expression increased in mesenteric white adipose tissue and played a role in cancer cachexia-related systemic inflammation." (PMID 35204186, 2022). "After being treated with PD-L1 antibody, the tumor escaped, and the IFNγR2-mutant tumor cells indeed proliferated." (PMID 35541919, 2022). "We postulate that IFNγR2 induction in Myc-CaP cells makes them more responsive to IFNγ secreted by tumor-infiltrating CTLs." (PMID 33602823, 2021). "Nonetheless, when a mixture of wild-type (WT) and IFNγR-mutant tumor cells was implanted in vivo to mimic the tumor heterogeneity often seen in patients, anti-PD-L1 therapy selected for outgrowth of the IFNγR2-mutant tumor cell clones." (PMID 32001684, 2020). "For further verification of the expression of CD4/IFNGR2/CD68/CSF1R as immune signatures in OSA tumor microenvironment, RT-qPCR was performed using mRNA from 45 collected primary surgical tissue samples of OSA primary tumors." (PMID 32850346, 2020). "Restored expression of PD-L1 in IFNγR2- and Jak1-mutant tumor cells re-established the progressive growth kinetics comparable to WT tumors." (PMID 32001684, 2020). "Similar to the B16.SIY model, IFN-γ-insensitive MC38 tumors exhibited slower tumor growth in vivo, which was reversed after the reintroduction of IFNγR2." (PMID 32001684, 2020). "To determine if the spontaneous tumor control was dependent upon adaptive immunity, we inoculated Rag2–/– mice with WT, IFNγR2-, or Jak1-mutant tumor cells and tracked tumor growth." (PMID 32001684, 2020). "When these tumors were harvested and re-analyzed by flow cytometry, selection for the IFNγR2-mutant tumor cells was observed in 12/15 of these cases." (PMID 32001684, 2020). "In order to assess the behavior of IFNγR2- and Jak1-mutant tumor cells in vivo, we subcutaneously implanted mutant or WT tumor cells into C57BL/6 mice and tracked tumor growth." (PMID 32001684, 2020). "To validate our initial in vitro CRISPR/Cas9 screen we exposed IFNγR2- and Jak1-mutant tumor cells to activated 2 C/Rag2–/– T cells to evaluate lysis." (PMID 32001684, 2020). "Consistent with our previous observation, the total number of H-2Kb/SIY+ CD8+ TILs correlated with selection for IFNγR2-mutant tumor cells." (PMID 32001684, 2020).
tumor (continued). "Findings: We identified the heterogeneity underlying tumor immune signature in OSA, and found CD4+ T cells and macrophage markers CD4/IFNGR2/CD68 to be feasible prognostic factors, exerting significantly positive correlation with each other." (PMID 32850346, 2020). "In fact, a greater frequency of H-2Kb/SIY+ CD8+ TILs correlated with a greater fraction of IFNγR2-mutant tumor cells emerging." (PMID 32001684, 2020). "Many of the differentially expressed genes found were shared between IFNγR2- and Jak1-mutant tumor cells." (PMID 32001684, 2020). "We observed a 3.9-fold increase in the frequency of IFNγR2-mutant tumor cells after IFN-γ administration compared to mice that did not receive IFN-γ." (PMID 32001684, 2020). "To this end, we mutated IFNγR2 and Jak1 in B16F10 tumor cells using the same single-cell method and confirmed successful disruption of IFN-γ signaling." (PMID 32001684, 2020). "In approximately half (15/28) of mice with WT:IFNγR2-mutant mixed tumors that received anti-PD-L1 therapy, the tumor escaped." (PMID 32001684, 2020). "In fact, we found that in the 12 mice where selection of IFNγR2-mutant tumor cells occurred, the frequency of H-2Kb/SIY+ CD8+ TILs was greater compared to the three mice that grew out WT tumor cells." (PMID 32001684, 2020). "We reasoned that this immune selection for IFNγR2 mutants would occur most robustly in the presence of a strong tumor-antigen-specific CD8+ T cell response, as the selection mechanism would involve direct tumor cell recognition of antigen." (PMID 32001684, 2020). "We first measured PD-L1 expression on the host and tumor compartments in WT, IFNγR2-, and Jak1-mutant tumors following implantation in vivo." (PMID 32001684, 2020). "To test this, we deleted the H-2Kb gene from the IFNγR2-mutant tumor cells by CRISPR/Cas9 mutagenesis and tracked tumor growth." (PMID 32001684, 2020). "Under this premise, we reasoned that the relative intratumoral quantity of IFN-γ would correlate with the selection of IFNγR2-mutant tumor cells." (PMID 32001684, 2020). "We found that the concentration of intratumoral IFN-γ positively correlated with both selection of IFNγR2-mutant tumor cells and also the frequency of SIY/H-2Kb CD8+ TILs." (PMID 32001684, 2020). "Worse survival outcomes in pbDMG patients when comparing high versus low TGFB2 levels in the context of low IFNGR2 levels suggest that the abrogation of the TGFB2 mRNA expression in the immunologically cold tumor microenvironment can be used to treat pbDMG patients." (PMID 38255296, 2024). "We also found that IFNGR2, IQCE, TRPM4, and SLX4 could be associated with SNU-16 derived tumor growth in female mice by endogenous E2." (PMID 34257587, 2021). "We confirmed the loss of IFN-γ signaling in IFNγR2- and Jak1-mutant MC38 tumor cell clones." (PMID 32001684, 2020). "Knowing that CD8+ T cells were the mediator of tumor control we next sought to determine whether CD8+ TILs exhibited improved effector functions in the context of IFNγR2- or Jak1-mutant tumors." (PMID 32001684, 2020). "Therefore, we depleted CD8+ T cells, NK cells or both with depleting antibodies in C57BL/6 mice 1 day before and 5 and 10 days after engrafting WT or IFNγR2-mutant tumor cells." (PMID 32001684, 2020). "To further test the role of IFN-γ in tumor cell selection, we reasoned that administration of additional IFN-γ could push the system further towards IFNγR2-muant tumor cells." (PMID 32001684, 2020). "To better align our mouse model with this clinical scenario, we found that when WT tumor cells were mixed with IFNγR2-mutant tumor cells and implanted in vivo, the IFNγR2-mutant cells were indeed selected out under strong immune pressure upon anti-PD-L1 therapy." (PMID 32001684, 2020). "To test this hypothesis, we retrovirally restored expression of PD-L1 in IFNγR2- and Jak1-mutant tumor cells." (PMID 32001684, 2020).